OSMR (oncostatin M receptor)
Diseases named in the same sentence as OSMR in open-access papers (continued):
Sharing a sentence is not in itself a finding about the gene and the disease.
gastric cancer (7 papers, 2010 to 2023). A primary or metastatic malignant neoplasm involving the stomach. "The high expression of OSMR in tumor cells was closely correlated with lymph node metastasis of gastric cancer." (PMID 37333017, 2023). "SP1 is shown to transcriptionally regulate oncostatin M receptor in gastric cancer and thereby contribute to cancer progression." (PMID 36033825, 2022). "Then, we selected and validated three genes including THBS2, OSMR and CHI3L1 in Iranian gastric cancer patients." (PMID 33585016, 2020). "OSMR, LRP6, and SERPINF1 were expressed in most gastric cancer samples." (PMID 37333017, 2023). "Upregulation of THBS2, OSMR and CHI3L1 was verified in EMT-induced gastric cancer cell line." (PMID 33585016, 2020). "Furthermore, significant upregulation of candidate genes including THBS2, OSMR and CHI3L1 verified the role of these proteins in gastric cancer invasiveness." (PMID 33585016, 2020). "Moreover, OSMR expression exhibited a significant negative correlation with E-cadherin levels and a positive correlation with N-cadherin expression in gastric cancer samples from TCGA, and the results were validated by IHC analysis in an independent cohort." (PMID 34361105, 2021). "In addition to ERBB2 and PERLD1, the TRAC analysis also identified five novel genes, CYP3A4, ENAH, MMP9, PTPRA, and OSMR, which have not been reported as gained and overexpressed in gastric cancer before." (PMID 20187983, 2010).
colorectal cancer (6 papers, 2009 to 2023). A primary or metastatic malignant neoplasm that affects the colon or rectum. "OSMR is active in a wide range of solid tumor cell lines, including breast tumor, colorectal cancer, bone carcinoma, and so on." (PMID 30755233, 2019). "In this study, we identified PAPSS2, TUBG2, NTRK2, B4GALT1 and OSMR as genes harboring cancer-specific promoter methylation in human colorectal cancer." (PMID 19662090, 2009). "The first connection of OSM in colorectal cancer was through discovering that the OSMR gene is highly methylated in non-invasive colorectal cancer patients, but not in normal controls, and has been suggested as a highly specific prognostic marker for colon cancer detection and severity of disease." (PMID 37841259, 2023). "The highlights the tumor-suppressive role of OSMR in colorectal carcinoma." (PMID 30755233, 2019). "OSMR may be a tumor suppressor in colorectal cancer, and methylation OSMR may play a catalytic role in non-invasive colorectal cancer." (PMID 36142828, 2022).
heart failure (5 papers, 2017 to 2025). Inability of the heart to pump blood at an adequate rate to meet tissue metabolic requirements. "Moreover, sustained activation of the OSMR/gp130 cascade is associated with macrophage infiltration and the development of heart failure in adult patients with various chronic heart diseases." (PMID 37120549, 2023). "Similar to animal studies, sustained activation of the OSMR/gp130 cascade correlates with macrophage infiltration and the development of heart failure in adult patients with various chronic cardiac diseases." (PMID 35163735, 2022). "Short-term activation of OSMR/gp130 protects the heart after acute injury, whereas chronic activation promotes the development of heart failure." (PMID 35163735, 2022). "OSMR deficiency aggravated pressure overload-induced cardiac hypertrophy by modulating macrophages and OSM/LIFR/STAT3 signalling, which provided evidence that OSMR might be an attractive target for treating pathological cardiac hypertrophy and heart failure." (PMID 37120549, 2023). "Some C/EBPβ target genes, for example, OSMR, MAP2K3 and CDKN1B also have been studied in heart failure developmental progress." (PMID 32460775, 2020). "Also, some C/EBPβ target genes, for example, OSMR, MAP2K3 regulate the heart failure developmental progress." (PMID 32460775, 2020).
inflammatory bowel disease (5 papers, 2019 to 2023). A spectrum of small and large bowel inflammatory diseases of unknown etiology. "The reason for the inflammatory signaling pathways predominant in MG is probably because the inflammatory bowel disease (IBD) risk genes (e.g., SMAD3 and OSMR) were significantly expressed in MG." (PMID 36693960, 2023). "In inflammatory bowel disease (IBD), OSM and its receptor (OSMR) are expressed in high levels in inflamed intestinal tissue, and levels are correlated with histopathological disease severity and CRP levels." (PMID 30621017, 2019).
Obesity (5 papers, 2017 to 2023). Accumulation of substantial excess body fat. "Oncostatin M (OSM) is another proinflammatory cytokine that is elevated in AT in human obesity, and its specific receptor (OSMRβ) is also induced in conditions of obesity and insulin resistance." (PMID 33854494, 2020). "While OSM KO and OSMRβ KO mice are healthy and fertile, phenotypical changes observed are a disturbed hematopoiesis in both KO strains and severe obesity upon a high-fat diet in OSMRβ KO animals." (PMID 31191538, 2019). "Interestingly, OSM is elevated in human obesity, and its specific receptor (OSMRβ) is also induced in conditions of obesity and insulin resistance." (PMID 37238642, 2023). "Previous work from our laboratory showed that OSMR-β could regulate obesity-induced metabolic disorders of hepatic and cerebral ischemia/reperfusion injury in a STAT3-dependent manner." (PMID 28258089, 2017). "In addition, disruption of the OSMR gene in mice results in the development of mature onset obesity and systemic insulin resistance by regulating the function of macrophages." (PMID 28258089, 2017). "CNTNAP2, GLI2, DPT (dermatopontin), AEBP1, ITIH5, CXCL11, GDNF (glial cell derived neurotrophic factor), MCHR1, FLT3, ELANE (elastase, neutrophil expressed), OSMR (oncostatin M receptor) and IL15RA are involved in development of obesity, but these genes might be key for progression of HF." (PMID 34218797, 2021).
ovarian carcinoma (5 papers, 2022 to 2025). A malignant neoplasm originating from the surface ovarian epithelium. "More recent research however has further evaluated the role of OSM in ovarian cancer and found that OSMR is highly expressed in ovarian cancer cells, cancer associated fibroblasts, and endothelial cells of patient samples, and is highly expressed when compared to normal adjacent tissues." (PMID 37841259, 2023). "In ovarian cancer, OSMR promotes tumor cell proliferation and metastasis by activating the STAT3 signaling pathway, and monoclonal antibodies targeting OSMR effectively suppressed cancer cell growth." (PMID 41498024, 2025). "We observed that our antibodies reduced the cell viability of cisplatin-resistant ovarian cancer cells considerably which was relying on OSMR signaling and therefore showed sensitization towards cisplatin therapy both in vitro and in vivo." (PMID 38839865, 2024). "In the current study, we determined the potential of using our anti-OSMR antibody to sensitize cisplatin treatment to treat cisplatin-resistant ovarian cancer." (PMID 38839865, 2024). "In the current study, we identified that OSMR is one of the highly upregulated genes in chemoresistant ovarian cancers particularly in the ovarian cancer cells expressing high levels of cancer stemness markers and EMT characteristics." (PMID 38839865, 2024). "Our recent work has reported that OSMR is a critical regulator of oncogenic addiction mechanism in ovarian cancer cells." (PMID 38839865, 2024). "Taken together, our results underscore the pivotal role of OSMR as a requirement for cisplatin resistance in ovarian cancer." (PMID 38839865, 2024). "Taken together, our findings have provided new insights on the role of OSM-OSMR signaling in promoting cisplatin resistance in ovarian cancer and opportunities to reverse cisplatin-resistant mechanisms in ovarian cancer through targeting anti-OSMR antibodies." (PMID 38839865, 2024). "Next, we confirmed the effect of anti-OSMR B21 mAb on inhibiting the growth of cisplatin-resistant ovarian cancer cells and sensitizing the efficacy of cisplatin in vivo." (PMID 38839865, 2024). "On this background, we have characterized how the integrin signaling is regulated by OSMR in ovarian cancer cells and the potential of inhibiting OSMR for cisplatin sensitization." (PMID 38839865, 2024). "Anti-OSMR antibody inhibited the growth of ovarian cancer cells in vitro and in vivo by suppressing STAT3 activation." (PMID 35565185, 2022). "Taken together, our results demonstrate that OSMR is an important mediator of cell survival and chemoresistance mechanism in ovarian cancer cells and inhibiting the oncogenic actions of OSMR using OSMR-specific antibody was able to sensitize cisplatin treatment." (PMID 38839865, 2024). "Therefore, we sought to determine the role of integrins in promoting chemoresistance and characterize the mechanism of how integrin signaling is regulated by OSMR in cisplatin resistant ovarian cancer cells." (PMID 38839865, 2024). "Notably, targeting OSMR using anti-OSMR human antibody inhibited the growth and metastasis of ovarian cancer cells and sensitized cisplatin treatment." (PMID 38839865, 2024). "We found that our anti-OSMR monoclonal antibodies reduced the ovarian cancer cell growth and progression by inhibiting STAT3 activation and subsequent oncogenic signaling operated through STAT3, inhibiting the levels of survival regulators such as BCl2, PCNA, and inducing cell death." (PMID 38839865, 2024). "We next performed colony forming assay to determine if OSMR knockdown could sensitize the cisplatin resistant ovarian cancer cells to cisplatin therapy." (PMID 38839865, 2024). "While we noticed a decrease in colony formation in the cisplatin-resistant ovarian cancer cells, we also observed an improved level of inhibition in the colony forming ability of cisplatin resistant cells when OSMR was stably knockdown alone and in combination with cisplatin." (PMID 38839865, 2024).
ovarian carcinoma (continued). "Given that the receptors and ligands that activate the autocrine signaling through OSMR are highly expressed in cisplatin-resistant ovarian cancer cells, we sought to determine the level of OSMR/IL6ST heterodimerization in the cisplatin resistant cells compared to the sensitive cells." (PMID 38839865, 2024). "Therefore, targeting OSMR emerges as a promising and viable strategy to reverse cisplatin-resistance in ovarian cancer." (PMID 38839865, 2024). "Additionally, the same group analyzed 25 primary ovarian carcinomas samples (OC) for LIFRβ and OSMRβ expression and found all 25 primary OC samples expressed LIFRβ and 14 out of 25 expressed OSMRβ." (PMID 37841259, 2023). "Next, we elucidated whether the overexpression of OSMR can induce chemoresistance in ovarian cancer cells, where we treated ovarian cancer cells with cisplatin and determined inhibitory concentrations of cisplatin in both sensitive and OSMR overexpressing cells using CCK8 cell viability assay." (PMID 38839865, 2024). "In consistent with mRNA data, protein levels of OSMR and its dimerizing partner IL6ST are highly upregulated in cisplatin-resistant A2780, OVCAR8, PEO4 and MCW-OV-SL3 ovarian cancer cell lines compared to their respective controls." (PMID 38839865, 2024). "Taken together, our results suggest that OSMR is critical modulator of cell survival, cancer stemness and EMT, and chemoresistance in ovarian cancer cells." (PMID 38839865, 2024). "Notably, we found that OSMR, LIFR, IL6R, and IL6ST mRNA were highly upregulated in cisplatin-resistant ovarian cancer cells in both A2780 and OVCAR8 cells." (PMID 38839865, 2024). "We characterized that the crosstalk between OSMR and integrins through their interactions with respective ligands like OSM or fibronectin (FN) leads to the activation of STAT3 transcription factor for prolonged period in chemo resistant and highly aggressive ovarian cancer cells." (PMID 38839865, 2024).
atherosclerosis (4 papers, 2017 to 2022). A disease characterized by the build-up of fatty material and calcium deposition in the arterial wall resulting in partial or complete occlusion of the arterial lumen. "Taken together, these data suggest that the loss of OSMR-β attenuates the development of atherosclerosis, at least partly, via inhibiting the JAK2/STAT3 signal transduction pathway in macrophages." (PMID 28258089, 2017). "Together, these results demonstrate that OSMR-β deficiency in macrophages attenuated the development of atherosclerosis." (PMID 28258089, 2017). "More importantly, we discovered that OSMR-β deficiency attenuated the development of atherosclerosis and improved plaque stability partially through the inhibition of JAK2/STAT3 signaling." (PMID 28258089, 2017). "Furthermore, in ApoE-/- mice, OSMR deficiency attenuated atherosclerosis development and increased plaque stability." (PMID 31461490, 2019). "Mech­anistically, the protective effect of OSMR-β deficiency on atherosclerosis may be partially attributed to the inhibition of the JAK2/STAT3 activation in macrophages, whereas OSM stimulation can activate the signaling pathway." (PMID 28258089, 2017). "Therefore, we demonstrated that OSMR-β deficiency in macrophages reduced the severity of atherosclerosis by decreasing inflammation." (PMID 28258089, 2017). "With these data, the present study provides cumulative evidence that OSMR-β has an important effect on the development of atherosclerosis, but the potential mechanism through which OSMR-β deficiency confers an atheroprotective effect remains unclear." (PMID 28258089, 2017). "Mechanistically, the role of OSMR-β in the development of atherosclerosis is partially mediated through regulation of the JAK2/STAT3 signaling pathway." (PMID 28258089, 2017). "To identify a potential molecular mechanism by which OSMR-β accelerated the development of atherosclerosis, we examined the activation state of the JAK-STAT signaling pathway." (PMID 28258089, 2017). "Considering that OSMR-β expression was significantly increased in the aortas of ApoE−/− mice fed a HFD, we proposed that endogenous OSMR-β plays a critical role in the development of atherosclerosis." (PMID 28258089, 2017). "In this context, preventing the activation of the OSMR-β signaling pathway in macrophages could represent a new strategy for attenuating atherosclerosis." (PMID 28258089, 2017). "Here, we found enhanced OSMR-β expression during atherosclerosis in humans and mice." (PMID 28258089, 2017). "Moreover, bone marrow transplantation of OSMR-β−/− hematopoietic cells to atherosclerosis-prone mice displayed a consistent phenotype." (PMID 28258089, 2017). "However, whether increased OSMR-β is part of a compensatory mechanism or a key regulatory factor in the development of atherosclerosis requires further elucidation." (PMID 28258089, 2017). "Moreover, murine studies showed that OSM receptor (OSMR)−/−ApoE−/− mice have reduced plaque size and improved plaque stability compared to their OSMR-expressing littermates, indicating that OSM drives atherosclerosis development." (PMID 33959646, 2021). "Finally, we focused on only three genes (OSM, OSMR and LIFR), while atherosclerosis is a multifactorial disease." (PMID 33959646, 2021). "Taken together, these results demonstrated that OSMR ablation in ApoE−/− mice attenuated HFD-induced atherosclerosis and that this effect was not dependent on dyslipidemia." (PMID 28258089, 2017). "Second, OSMR-β deficiency protected mice against HFD-induced atherosclerosis, and BMT demonstrated that the absence of OSMR-β from bone marrow-derived cells improved atherosclerosis." (PMID 28258089, 2017).
cervical squamous cell carcinoma (4 papers, 2013 to 2023). A squamous cell carcinoma arising from the cervical epithelium. "The overexpression of OSM and OSMR in cervical squamous cell carcinoma (SCC) can also cause a variety of malignant effects, including infiltration and production of angiogenic factors and associated with poor clinical outcomes." (PMID 34422217, 2021). "Oncostatin M receptor (OSMR) is commonly over-expressed in advanced cervical squamous cell carcinoma (SCC), producing a significantly worse clinical outcome." (PMID 23765377, 2013). "An exciting new molecular target for the treatment of cervical squamous cell carcinoma (SCC), and possibly for SCCs at other anatomical sites, is the oncostatin M receptor (OSMR)." (PMID 24659184, 2014).
Insulin resistance (4 papers, 2015 to 2023). Increased resistance towards insulin, that is, diminished effectiveness of insulin in reducing blood glucose levels. "Results from the first study indicate that OSMRβ KO mice exhibit AT inflammation, insulin resistance, increased hepatic and serum lipid concentrations, and beta cell hyperplasia on normal chow diet." (PMID 25689119, 2015). "This suggests that paracrine OSM signalling within the AT supports immune cell homeostasis and its disruption in the OSMRβ knock-out mice may have contributed to a number of adverse secondary effects, including the development of insulin resistance." (PMID 35531859, 2022).
Pruritus (4 papers, 2021 to 2024). Pruritus is an itch or a sensation that makes a person want to scratch. "Pruritus intensity is also closely related to the dermal expression of IL-31RA and OSMRβ (oncostatin M beta receptor)." (PMID 38493053, 2024). "The number of IL-31RA+ or OSMRβ+ cells is also correlated with pruritus intensity in patients with bullous pemphigoid." (PMID 33924978, 2021). "Evaluating IL-31 role in pruritus pathogenesis have to necessarily consider both the plasmatic interleukin and its relative receptors: IL-31 receptor A and the oncostatin M receptor." (PMID 34118946, 2021). "These MrgprC11+ sensory nerve fibers mostly coexpress IL-31 receptor (IL-31RA/OSMRβ), which signals IL-31-induced pruritus to DRG neurons, the spinal cord, the hypothalamic tract and finally to the brain." (PMID 33924978, 2021). "IL-31 binds to IL-31 receptor (IL-31RA/OSMRβ) and activates JAK1/JAK2 and downstream STAT3 (to a lesser extent STAT1 and STAT5), then induces pruritus." (PMID 33924978, 2021). "Moreover, OSMRβ expression in the dermis is increased, although it is not correlated with the intensity of pruritus." (PMID 38493053, 2024).
acute kidney injury (3 papers, 2020 to 2023). Sudden and sustained deterioration of the kidney function characterized by decreased glomerular filtration rate, increased serum creatinine or oliguria. "LINC00520 sponging miR-27b-3p regulates OSMR expression to stimulate acute kidney injury via mediating the PI3K-Akt pathway." (PMID 33591944, 2021). "In addition, LINC00520 promotes the development of acute kidney injury by targeting miR-27b-3p and regulating OSMR expression through the PI3K/AKT signaling pathway." (PMID 37516879, 2023). "miR-27b-3p has been reported to be downregulated in acute kidney injury (AKI) and LINC00520 promotes the development of AKI by modulating miR-27b-3p/Oncostatin M Receptor β (OSMR) axis through the PI3K/AKT pathway." (PMID 33292252, 2020).
atopic dermatitis (3 papers, 2013 to 2026). "Here we describe a patient presenting with elevated IgE levels, atopic eczema, chronic pulmonary aspergillosis, and bone fractures, homozygous for a rare missense variant in the oncostatin M receptor (OSMR) gene." (PMID 41783139, 2026). "In accordance with this, intervention in the binding of IL-31 to its specific receptor IL-31RA/OSMRβ by specific antibodies has been proven to inhibit the pruritus in atopic dermatitis and prurigo nodularis." (PMID 33924978, 2021).